LAT2 (linker for activation of T cells family member 2)
Diseases named in the same sentence as LAT2 in open-access papers (continued):
Sharing a sentence is not in itself a finding about the gene and the disease.
pregnancy diseases (1 paper, 2020). "Therefore, differential specificity of the applied inhibitors allowed for estimation of the contribution of LAT1 and LAT2 in materno‐foetal AA transfer and their potential impact in pregnancy diseases associated with impaired foetal growth." (PMID 33001560, 2020).
psoriasis (1 paper, 2023). An autoimmune condition characterized by red, well-delineated plaques with silvery scales that are usually on the extensor surfaces and scalp. "A similar approach is used in keratinocytes from patients with psoriasis, where deleting LAT1 controls skin inflammation, while CD4+ T cells use alternative amino acid transporters (LAT2 and LAT3)." (PMID 37274280, 2023).
sarcopenia (1 paper, 2021). Progressive decline in muscle mass due to aging which results in decreased functional capacity of muscles. "Previous studies have reported from primary tissue a decline in SNAT2 expression with ageing; for example, in both slow and particularly fast twitch skeletal muscle fibre types, the authors argue that a decline in SNAT2 (and LAT2) was a contributor to the pathology of sarcopenia." (PMID 33982880, 2021).
thyroid (1 paper, 2021). "Obtained half-maximal inhibitory concentrations also provided new insights, e.g., into the LAT specificity of the potent inhibitor JPH203 and on the potency of the thyroid hormones T3 and T4 to inhibit transport through human 4F2hc-LAT2." (PMID 34124158, 2021).
thyroid cancer (1 paper, 2023). "In particular, MCT10 was minimally expressed in all thyroid cancer cell lines tested, while LAT2 was overexpressed in cancers compared to nontumoral control cells." (PMID 36877008, 2023).
ulcerative colitis (1 paper, 2016). An inflammatory bowel disease involving the mucosal surface of the large intestine and rectum. "Four (80%) of the associated genes with these CpG sites have been linked to either ulcerative colitis (IL4R and SAA1) or CRC (LAT2 and SAA2)." (PMID 27006956, 2016).
tumor (36 papers, 2011 to 2025). "The barely detectable LAT2 expression in tumor-associated macrophages suggested that the effect of the BCH on macrophages is minimal." (PMID 36274066, 2022). "Following chemotherapy, macrophages secrete interleukin-18 (IL-18), which in turn upregulates L-amino acid transporter protein 2 (LAT2) expression in tumour cells." (PMID 40598593, 2025). "Treatment of tumor cells with leucine transporter L-amino acid transporter 2 (LAT2) inhibitors downregulated CD47 expression, thereby enhancing macrophage infiltration and phagocytosis of tumor cells." (PMID 40688069, 2025). "The proposed KMPAG signature underscores the importance of three genes—CLEC4A, CXCL10, and LAT2—in modulating tumor–immune crosstalk and predicting patient outcomes." (PMID 40607411, 2025). "L-type amino acid transporter 1 (LAT1) is part of system L amino acid transporter subtype (LAT1, LAT2, LAT3, and LAT4) and is closely associated with tumor cell proliferation, angiogenesis, and survival across various human neoplasms." (PMID 39290273, 2024). "Here, we found that macrophage-secreted IL-18 upregulated LAT2 in tumor cells, which enhanced the uptake of Gln and Leu to upregulate CD47 for inhibition of macrophage phagocytosis." (PMID 36274066, 2022). "The aim of the present study was to confirm our previous findings regarding LAT1 and LAT2 expression in Pheo in a larger series of patients and to examine the relationship between LATs and the tumor secretory properties and 18F-DOPA-PET uptake parameters." (PMID 35269556, 2022). "Compared with doxorubicin treatment or LAT2 depletion alone, combination of LAT2 depletion with doxorubicin treatment greatly blunted tumor growth with increased infiltration of macrophages and enhanced activation of macrophages with M1 phenotype." (PMID 36274066, 2022). "Namely, cellular accumulation of these tracers is mainly driven by the activity of System L amino acid transporters (LAT1 and LAT2) that carry these amino acids into the tissue with unique metabolic pathways that can be exploited in tumor imaging." (PMID 35453892, 2022). "Recently, LAT1 of the L-type family of amino acid transporters has been shown to be present in tumor cells, while LAT2 is found in normal cells." (PMID 36464732, 2022). "Depletion or Inhibition of LAT2 in tumor cells abrogated IL-18-induced suppression of macrophage phagocytosis and improved antitumor immunity." (PMID 36274066, 2022). "The cellular uptake of radiolabeled amino acids is based on the expression of the sodium-independent large neutral amino acid transporters LAT1 and LAT2 on tumor cells." (PMID 33802292, 2021). "In general, the relative gene expression of Ki67, LAT1 and LAT2 in xenograft tumors were significantly different from the original patient tumor GBM_CPH048." (PMID 24918622, 2014). "Previous experimental data also demonstrated that LAT1 is overexpressed in tumor cells and LAT2 is dominantly expressed in normal cells." (PMID 24131658, 2013). "Similarly, LAT2 is involved in amino acid transport; investigating its role in metabolic crosstalk between tumor cells and immune cells, potentially under nutrient stress conditions like glutamine deprivation, would provide valuable mechanistic insights." (PMID 40607411, 2025). "Small‐molecule inhibitors of LAT2 reportedly inhibit CD47‐mediated tumor immune escape." (PMID 39778021, 2025). "Moreover, in vivo experiments showed that a combination curcumin and gemcitabine significantly reduced tumor size, tumor growth rate and LAT2 expression in a gemcitabine-resistant CCA xenograft mouse model." (PMID 38992159, 2024). "Moreover, our gemcitabine-resistant CCA model was consistent with in vitro results by suppressing tumor growth rate and LAT2 staining intensity." (PMID 38992159, 2024). "Notably, chemotherapy without CD47 blocking strategy enhances CD47 expression on tumor cells via inducing IL-18 release from macrophages, which increases L-amino acid transporter 2 (LAT2) in tumor cells." (PMID 37380989, 2023).
tumor (continued). "This could be associated with a higher risk for false-positive findings since recent studies revealed a crucial role of LAT1 in activated T cells and reported overexpression of the LAT1 in inflammation, while LAT2 is more tumor-selective." (PMID 35453892, 2022). "We reveal that macrophages in response to chemotherapy secrete interleukin-18, which in turn upregulates expression of L-amino acid transporter 2 (LAT2) in tumor cells for substantially enhanced uptakes of leucine and glutamine, two potent stimulators of mTORC1." (PMID 36274066, 2022). "In this regard, a potential explanation for the faster brain and tumor uptake kinetics of 3-l- compared to 3-d-[18F]FPhe could be the contribution of LAT2, which has been reported to transport only l amino acids." (PMID 34885141, 2021). "LAT2 has been reported to play different roles in multiple tumor types." (PMID 30419950, 2018). "Finally, we wanted to investigate the gene expression of Ki67, LAT1 and LAT2 in tumor specimens from GBM patients and compare it with the results from the xenograft tumors." (PMID 24918622, 2014). "If LAT2 primarily is located at the BBB, this could be a possible explanation for the low expression of LAT2 in xenografts as the LAT2 primers were specifically designed for human LAT2 and tumor vessels in the xenograft tumor are primarily murine." (PMID 24918622, 2014). "Expression of LAT2 and LAT3 mRNAs was lower in tumor tissue than in non-tumor tissue, and neither LAT2 nor LAT3 was associated with local invasion." (PMID 24168110, 2013). "In addition, we wanted to test the hypothesis that 18F-FET accumulation was correlated to the gene expression of LAT1 and/or LAT2 in the tumor." (PMID 24918622, 2014). "LAT2 increases glutamine and leucine uptake in tumor cells, increasing mTORC1 signaling and Myc-dependent CD47 upregulation on tumor cells." (PMID 37380989, 2023). "The large neutral amino acid transporters (LAT) like LAT1, LAT2, LAT3, and LAT4 are highly upregulated in tumor cells due to the full utilization of these transporters for tumor growth and development." (PMID 35295604, 2022). "Here, we identified a previously unreported therapeutic strategy to reduce CD47 expression by LAT2 inhibition and underscore the potential of LAT2 small-molecular inhibitors, such as BCH, in elimination of CD47-mediated tumor evasion." (PMID 36274066, 2022). "An increased 18F-DOPA uptake and tracer retention by Pheo is due to the tumor’s LAT1 and LAT2 overexpression, as previously shown by our group." (PMID 35269556, 2022). "The TCGA database showed that the expression of CD2, FGL2, LAT2, and SLAMF1 in tumor tissues was significantly lower than that in cancer tissues, which was confirmed by western blotting experiments." (PMID 35602471, 2022). "Consistent with our observations from in vitro experiment, LAT2 depletion greatly reduced the basal and doxorubicin-induced CD47 expression in tumor tissues." (PMID 36274066, 2022). "Mechanistically, chemotherapy promotes macrophage secretion of interleukin (IL)−18, which upregulates LAT2 expression in tumor cells and consequently enhances glutamine and leucine uptake- and mTOR activity-dependent CD47 expression for tumor immune envision." (PMID 36274066, 2022). "LAT1 and LAT2 form a heterodimer with the escort protein, 4F2hc (4F2 heavy chain, CD98), which is ubiquitously expressed, e.g. in tumours, brain, kidney, intestine, and placenta." (PMID 21835054, 2011). "The expression of L-type amino acid transporter 1 (LAT1) and L-type amino acid transporter 2 (LAT2) in tumor cells allows the amino acids to be uptaken regardless of BBB permeability, allowing for the visualization of non-contrast-enhancing tumors." (PMID 40710005, 2025). "Since there is no known drug substrate or inhibitor targeting LAT2 except for BCH, unfortunately, no studies have been conducted on LAT2 as a tumor-targeted therapy." (PMID 37047148, 2023).
tumor (continued). "It was found that the expression of LAT1 mRNA in tumor tissue was considerably higher than in non-tumor tissue, but the expression of LAT2 and LAT3 mRNA was lower." (PMID 35008399, 2022). "Clinical results in different tumor types indicate that transport mechanisms of FET may be more complex and one may speculate that FET is selectively transported by LAT2." (PMID 27559736, 2016). "In addition, the correlations between the 18F-FET tumor accumulation and the gene expression of Ki67 and the amino acid transporters LAT1 and LAT2 were investigated." (PMID 24918622, 2014). "Expression of LAT1 mRNA was significantly increased in tumor tissue compared with non-tumor tissue, while expression of LAT2 and LAT3 mRNAs was reduced." (PMID 24168110, 2013). "The TH transporters LAT1 and LAT2 are expressed in various tissues, e.g. in luminal and abluminal membranes of brain capillary endothelial cells, placenta, and intestine, whereas LAT1 also shows high expression levels in tumour cells." (PMID 21835054, 2011). "Consequently, enhancing the sensitivity of chemotherapy by inhibiting the uptake of LAT2-mediated amino acids to reduce CD47 and by enhancing the infiltration and phagocytosis of tumour cells by macrophages has emerged as a potential strategy for the treatment of cancer." (PMID 40598593, 2025). "Inhibiting L-amino acid transporter 2 (LAT2) or treating tumor cells with LAT inhibitors can downregulate the expression of CD47, enhance macrophage infiltration and phagocytosis of tumor cells, and improve cancer treatment by interfering with LAT2-mediated amino acid uptake." (PMID 40534850, 2025). "Interestingly, we found a strong negative correlation between the T/B ratio and the gene expression of LAT1 and LAT2 in xenografts, which may be explained by the 18F-FET kinetics and tumor cell retention mechanisms." (PMID 24918622, 2014). "In our database analysis, only LAT1 expression was tumor-dominant, and LAT2, LAT3, and LAT4 were similarly expressed in tumor and non-tumor tissues." (PMID 36900176, 2023). "As we did not perform IHC, we are unable to conclude if LAT1 and LAT2 were located primarily at the BBB, in the tumor cells or if the location is overlapping." (PMID 24918622, 2014). "As a result there would be a negative correlation between the T/B ratio and LAT1 and LAT2, although most of 18F-FET is still retained in the tumor cells as demonstrated in the dynamic 18F-FET PET." (PMID 24918622, 2014).
cancer (30 papers, 2014 to 2025). A tumor composed of atypical neoplastic, often pleomorphic cells that invade other tissues. "Increased LAT2‐mediated AA uptake is associated with poor overall survival in different types of cancer." (PMID 40546137, 2025). "A particular interest is the SLC7A6 gene, which encodes LAT2, a key glutamine transporter, which has been implicated in cancers." (PMID 35967756, 2022). "Specifically, we identified that SLC7A8 (LAT2) regulates the glutamine mechanism pathway involved in cancer progression." (PMID 38992159, 2024). "This is consistent with our previous observations that a combination of the cationic amino acid uniporter cat-1 and y+LAT2 can serve as a tertiary active transport mechanism to import neutral amino acids into cancer cells." (PMID 36830670, 2023). "LAT2 is reported to be less distributed in malignant tumors except for neuroendocrine tumors and more distributed in normal tissues." (PMID 37047148, 2023). "The Wilcoxon signed rank test was applied to compare the difference in LAT2 expression between the 71 cancer and matched paracancerous tissues." (PMID 30419950, 2018). "Further studies are needed to define if the LAT1/LAT2 overexpression is also the molecular basis for justifying the 18F-FDOPA use in functional imaging of NET cancers." (PMID 27224648, 2016). "However, compared with LAT1, there is less evidence to support the general role of LAT2 in cancer, and it is more likely to be used as a benign biomarker." (PMID 37047148, 2023). "The roles of LAT2 have been widely studied in different cancers." (PMID 34976784, 2021). "Four subtypes of LATs have been identified of which subtype 1 (LAT1) and subtype 2 (LAT2) have been related to the cellular uptake of 18F-FET in cancer cells, although it has been speculated that 18F-FET accumulation primarily is mediated by LAT2." (PMID 24918622, 2014). "Down-regulation of LAT2 may reduce glutamine uptake of the cancer cells." (PMID 38992159, 2024). "So far, four LATs (LAT1, LAT2, LAT3, and LAT4) have been identified, and blocking LAT1 has become an attractive strategy in cancer therapy." (PMID 36274066, 2022). "The possibility that targeting LAT1 stimulates the compensatory upregulation of a different LAT transporter (i.e., LAT2, LAT3, or LAT4), or a different transporter system (i.e., SNAT amino acid transporters) in certain cancers also warrants investigation." (PMID 30103560, 2018). "It has been reported that cancer cells highly express an L-type amino acid transporter 1 (LAT1), whereas normal cells highly express LAT2." (PMID 27977675, 2016). "While LAT2 is ubiquitously distributed in normal tissues, particularly in renal proximal tubules and small intestinal epithelium, LAT1 is highly expressed in various cancers and is also present in the blood–brain barrier (BBB) and placental barrier." (PMID 38409393, 2024). "Conversely, hydrophilic BPA is mainly taken up by the cancer cell line via the L-amino acid transporter-1 (LAT-1), which is overexpressed in cancer cells, with a small amount also being transported by the LAT-2, which is overexpressed in both cancer cells and normal cells." (PMID 36291173, 2022). "The HAT 4F2hc-LAT1 is found upregulated in various cancer cell types, while 4F2hc-LAT2 is a transporter for non-cancer cells." (PMID 34124158, 2021). "When considered as a treatment for cancer, the inhibitory effect of BCH to LAT2 is problematic because LAT2 is mainly expressed in normal cells and BCH may interfere with the function of normal cells." (PMID 31992742, 2020). "Therefore, transport inhibitors with high specificity towards 4F2hc-LAT1 but not -LAT2 represent promising drug candidates for cancer therapy and diagnosis." (PMID 34124158, 2021). "Double staining showed that many cancer cells tended to coexpress LAT1 and Ki-67, but not LAT2 and Ki-67." (PMID 24890221, 2014).
infection (3 papers, 2021 to 2024). The state of being infected such as from the introduction of a foreign agent such as serum, vaccine, antigenic substance or organism. "However, jejunal B0AT, B0+AT, GLUT1, LAT2, and SGLT levels were not changed (p > 0.05) by infection or dietary ICOOH supplementation." (PMID 35812452, 2022).
metabolic disorders (1 paper, 2025). "Understanding the role of LAT2 in different cell types and metabolic conditions may have significant clinical implications for age‐related diseases and metabolic disorders." (PMID 40546137, 2025).
LAT2 also shares sentences with these, for which no sentence is quoted: acute myeloid leukemia (2 papers); lysinuric protein intolerance (2); Medullary Thyroid Carcinoma (2); acute promyelocytic leukemia (1); allergic disease (1); allergic rhinitis (1); ampullary adenocarcinomas (1); asthma (1); basophilic leukemia (1); bile duct cancer (1); chronic kidney disease (1); folate deficiency (1); gestational diabetes (1); Gliosis (1); hematological malignancies (1); hilar cholangiocarcinoma (1); Hyperglycemia (1); hyperthyroidism (1); intrahepatic cholangiocarcinoma (1); latent infections (1); lymphoid neoplasm (1); mantle cell lymphoma (1); myeloid leukemia (1); neurodegenerative disease (1); Obesity (1); pheochromocytoma (1); Primary Immunodeficiency (1); renal cell carcinoma (1); rheumatoid arthritis (1); skeletal disease (1).
A further 5 diseases each share a sentence with LAT2 in 1 paper.